CD5 (CD5 molecule)
Diseases named in the same sentence as CD5 in open-access papers (continued):
Sharing a sentence is not in itself a finding about the gene and the disease.
T-cell leukemia (13 papers, 2013 to 2025). A malignant disease of the T-lymphocytes in the bone marrow, thymus, and/or blood. "We screened various anti-CD5 scFvs and selected the top four cells with high binding efficiency against CD5-expressing T cell leukemia cell line Jurkat to obtain CD5 CAR-NK cells with enhanced efficacy against cells expressing the target antigen." (PMID 41050660, 2025). "The lack of significant immunosuppression and the in vitro/in vivo efficacy of anti-CD5 CARTs/CARNKs open the gate to investigating further possibilities regarding the adoption of cell therapy utilizing this antigen for T cell leukemias and lymphomas." (PMID 33384022, 2020). "Anti-CD5 monoclonal antibodies linked to momordin (a ribosome-inactivating protein purified from M. charantia) performed better than other anti-CD5-based immunoconjugates containing ricin A chain on human T cell leukemia Jurkat." (PMID 29182587, 2017). "Moreover, NK-92 cells, a CD5-negative NK cell line, were utilized to enhance cytotoxicity against T-cell leukemia via CD5-CAR, which significantly improved survival in a T-ALL xenograft model." (PMID 38915099, 2024). "In this sample, we found a uniform expansion (89% in CD45+ cells) of CD5+CD21– cells, which represents a T cell leukemia." (PMID 36996049, 2023). "have tested NK-cell and CD5-depleted Jurkat T cell lines as CAR carriers in the treatment of T cell malignancies in vitro and in a xenograft T cell leukemia mice model." (PMID 33384022, 2020). "CARs targeting CD5 or CD3 that are delivered into the NK-92 cell line have been found to have efficient cytotoxic activity against primary peripheral T cell lymphoma cells and T cell leukemia cell lines." (PMID 34215336, 2021). "Raji cell line was used as negative control without expression of CD5, while the cell lines of T cell leukemia Jurkat and CCRF-CEM, the cell lines of MCL Jeko-1 and CD5+ Raji were used as target cell lines." (PMID 39462383, 2024).
lymphoproliferative disorder (12 papers, 2013 to 2025). "An example of this type of combination is a CD5+/CD23+ phenotype which occurs in many lymphoproliferative disorders, such as CLL and NHL." (PMID 38672662, 2024). "They developed a lymphoproliferative disorder characterized by the expression of CD5 and the utilization of unmutated IGHV genes, thus resembling human U-CLL." (PMID 36430731, 2022). "We also calculated the proportion and number of CD5+ CD19+ B cells (also known as B1 cells) as this subset is associated with various autoimmune and lymphoproliferative disorders, and was shown to be expanded in a cohort of HCV patients." (PMID 23840845, 2013). "In cases with a typical immunophenotype, a panel that includes CD19, CD5, CD20, CD23, and kappa and lambda light chain renders the diagnosis; however, larger panels are often used to further support the diagnosis and allow the differentiation with other CD5 positive lymphoproliferative disorders." (PMID 37606492, 2023). "High uncertainty values would automatically flag cases with unusual or ambiguous immunophenotypic features for closer expert review, potentially improving the detection of CD5-negative lymphoproliferative disorders and other non-CLL neoplasms that currently challenge the DNN." (PMID 40427185, 2025).
anaplastic large cell lymphoma (11 papers, 2010 to 2024). Anaplastic large cell lymphoma (ALCL) is a rare and aggressive peripheral T-cell non-Hodgkin lymphoma, belonging to the group of CD30-positive lymphoproliferative disorders, which affects lymph nodes and extranodal sites. "Moreover, PBML can be identified as a special clinical phenotype in various study cohorts, including those considering cases of large cell lymphoma in the leukemic phase, the Asian‐variant of intravascular large B‐cell lymphoma, or de novo CD5(+) DLBCL." (PMID 29984910, 2018). "Histologically, all cases with T-cell marker(s) other than CD5 were categorized as large cell lymphomas, and showed atypical large lymphoid cell proliferation with a centroblastic or anaplastic morphology, positive for CD20." (PMID 28380441, 2017). "The unique feature of our case was the presence of de novo CD5 positive large cell lymphoma which has been described as a distinct entity with a very aggressive clinical course." (PMID 27777803, 2016). "In our retrospective review, there was one definitive case of a CD5-positive large cell lymphoma that was diagnosed by FNA, which was confirmed on histologic follow-up and found to be arising in a background of a small cell lymphoma compatible with SLL/CLL." (PMID 20976208, 2010). "In addition, we propose different criteria to diagnose large cell lymphoma, considering the percentage of large B-cells and their nFSC to diagnose large B-cell lymphoma, and the percentage of large T-cells and their CD5-nMFI to diagnose large T-cell lymphoma, respectively." (PMID 37368760, 2023). "Lymph node biopsy showed intermediate to large atypical monomorphic lymphocyte cells with ALK, CD30, CD5, CD3, CD45, and BCL-2 (weak positive) positivity and Ki-67-95%, suggestive of anaplastic large cell lymphoma (ALCL)." (PMID 38650799, 2024). "Anaplastic large cell lymphoma (ALCL) is an aggressive mature T-cell lymphoma that usually expresses the lymphocyte activation marker CD30 and often lacks expression of T-cell antigens, such as CD3, CD5, and CD71." (PMID 32587329, 2020).
lymphoplasmacytic lymphoma (11 papers, 2012 to 2026). A clonal neoplasm of small B-lymphocytes, lymphoplasmacytoid cells, and plasma cells involving the bone marrow, lymph nodes, and the spleen. "Lymphoplasmacytic lymphoma (LPL) can rarely be CD5-positive." (PMID 26201725, 2015). "The diagnosis was confirmed via biopsy (CD20+, CD5-, CyclinD1-) and negative MYD88 L265P mutation status, excluding lymphoplasmacytic lymphoma." (PMID 41800116, 2026). "Histopathological analysis by ultrasonography‐guided biopsy revealed dense lymphocytic proliferation, plasmacytoid differentiation, and Dutcher bodies, positive for CD20, CD138, and IgM, but negative for CD3 and CD5, consistent with lymphoplasmacytic lymphoma." (PMID 40336752, 2025). "Lymphoplasmacytic lymphoma (LPL) and the corresponding clinical entity Waldenström macroglobulinemia is one of the CD5 negative, CD10 negative small B-cell lymphomas that may involve the spleen." (PMID 34940069, 2021).
rheumatoid arthritis (11 papers, 2014 to 2025). A chronic, systemic autoimmune disorder characterized by inflammation in the synovial membranes and articular surfaces. "Intersection of GCLiPP and PICS2 data also revealed a probable causal SNP associated with rheumatoid arthritis in the 3′UTR of CD5, which encodes an inhibitory receptor expressed on T cells." (PMID 38062486, 2023). "Specifically, CD5 variation has been associated with rheumatoid arthritis (RA) susceptibility and the development of lupus nephritis." (PMID 35372412, 2022). "Proteomic analyses have demonstrated that CD5 exhibits remarkable specificity in the synovial fluid of patients with rheumatoid arthritis (RA) and KOA." (PMID 40429617, 2025). "For three of these genes—CD5, CTLA4, and SLAMF1—associations of rheumatoid arthritis with SNPs within 200 kb of the transcription site are listed in the GWAS catalog." (PMID 39887658, 2025). "In contrast, while CD5 is described to be a marker of B1a B cells that have been characterized to produce RF in rheumatoid arthritis patients, RF expressing B cells in HCV chronic infection are CD5-." (PMID 26649443, 2015). "For five of the 16 putative core genes—CD5, CTLA4, SLAMF1, PDCD1, and TNFRSF14—that were identified through association of GATE scores with rheumatoid arthritis, associations of rheumatoid arthritis with SNPs within 200 kb of the transcription site are listed in the GWAS catalog." (PMID 39887658, 2025).
T-cell acute lymphoblastic leukemia (10 papers, 2015 to 2025). Acute lymphoblastic leukemia of T-cell origin. "Targeting CD5 via CART is promising, as seen in the MAGENTA study and recent Phase I studies of donor-derived CD5 CAR T-cells in patients with relapsed or refractory T-cell acute lymphoblastic leukemia." (PMID 39410047, 2024). "A total of 25% of cases of this group were represented as T-cell ALL which characteristically expressed CD5, surface CD3 (sCD3) and CD4/CD8 dichotomy markers." (PMID 39113054, 2024). "CD5 has high expression in approximately 80% of T-cell acute lymphoblastic leukemia (T-ALL) and T cell lymphomas along and also has significant expression on B-cell lymphomas." (PMID 30031396, 2018).
multiple myeloma (9 papers, 2011 to 2025). "We examined BCR rearrangement in UPNs 14–17: UPNs15 and 16 had plasma cell myeloma and a small CD5+ B cell clone, respectively." (PMID 37586319, 2023). "This profiling is opposed to that reported in multiple myeloma in which these are increased, indicating that CD5-positive DLBCL has an immature B cell-lineage phenotype." (PMID 37705009, 2023). "Given that myeloma typically originates from CD5-negative, post-germinal center B2-cells, whereas murine CLL is believed to arise from the B1-lineage that express CD5, our goal was to examine the impact of the B1-cell compartment on myeloma development." (PMID 39198400, 2024). "A flow cytometric investigation of peripheral blood found an abnormal lambda monotypic B-cell population suggestive of B-CLL ([cluster of differentiation: CD] CD19+, CD22 dim+, CD23 dim+, CD5+CD19+, CD5+CD23+, FMC7−; negative for myeloma cells [CD45−/CD19−/CD38+/CD56+/CD138+])." (PMID 41226350, 2025).
Burkitt lymphoma (8 papers, 2014 to 2025). A rare form of malignant mature B-cell non-Hodgkin lymphoma. "Within the nodule, CD21, CD23, and CD35-positive follicular dendritic cells were scattered with a small number of CD3/CD5-positive small T-lymphocytes, indicating that the nodular architecture represented follicular colonization of Burkitt lymphoma cells." (PMID 34868769, 2021). "Other entities taking part in the differential diagnosis of Burkitt’s lymphoma include T lymphoblastic lymphoma/leukemia (expressing T cell markers and TdT) and blastoid mantle cell lymphoma (CD5 and cyclin D1 positive)." (PMID 25364378, 2014). "Then, to reach a final diagnosis of Burkitt’s lymphoma, immunohistochemical stainings should provide evidence that lymphomatous cells express CD19, CD20, CD10, and CD79a and no CD3, CD5, Bcl2, and TdT." (PMID 30453922, 2018). "Burkitt lymphoma typically also expresses CD10 and B-cell markers, surface light chain restriction, relatively bright expression of CD38, and CD43, without expression of CD5." (PMID 40075660, 2025). "Immunohistochemical and molecular studies demonstrated typical features of sporadic Burkitt lymphoma: the atypical cells were positive for CD20, CD79a, CD10, CD23, HLA-DR, bcl-6, PAX5, c-myc, and cytoplasmic IgM, but negative for CD3, CD5, CD15, CD30, CD34, TdT, bcl-2, and MUM1." (PMID 34868769, 2021).
influenza (8 papers, 2014 to 2024). An acute viral infection of the respiratory tract, occurring in isolated cases, in epidemics, or in pandemics; it is caused by serologically different strains of viruses (influenzaviruses) designated A, B, and C, has a 3-day incubation period, and usually lasts for 3 to 10 days. "In work co-submitted with this manuscript, Savage and colleagues show that TLR activation of B-1a cells both in vitro and in the context of influenza infection results in the loss of surface CD5 and a concomitant increase in BCR-downstream signaling." (PMID 31433298, 2019). "Beside the dependence of stimulating DC capacity on CD5, the authors also showed strengthened immune response against classical viral recall antigens (influenza, Epstein Barr and cytomegalovirus) when these were presented on CD5+ DCs." (PMID 37230972, 2023). "Consistent with the studies of MedLN B-1 cell populations after influenza infection, we found an increased number of B-1 cells in the infected Mesenteric LN (MesLN) of mice given CD5+ B-1 cells vs. those given CD5- B-1 cells (left)." (PMID 31433296, 2019). "The studies confirmed our previous findings that among CD19hiIgMb+IgDloCD43+B-1 cells in the MedLN, about 70% expressed CD5 after influenza infection." (PMID 31433296, 2019). "Furthermore, the CD5+ B-1a cell subset, which produces natural broad specificity anti-influenza IgMs that contributes to early protection, also normally accumulated in ICAM-1/2-/- MedLNs of PR8 infected mice." (PMID 36895258, 2022). "To reconcile our previous findings about the role of CD5+ B-1 cells in influenza infection, we considered whether CD5 surface expression may change after B-1 cell activation." (PMID 31433296, 2019). "The data would explain the increases in CD5- B-1 cells in the MedLN after influenza infection." (PMID 31433296, 2019). "To investigate the contribution of CD5- B cells to local IgM secretion, we FACS-sorted CD19+IgM+IgDloCD43+ CD5+ and CD5- B cells on days 3, 5, and seven after influenza infection from C57BL/6 mice, which were then cultured for 2 days to analyze spontaneous IgM secretion by ELISA." (PMID 31433296, 2019). "Indeed, complete TLR-deficient mice (due to a lack of TLR2, TLR4 and Unc93) showed significant deficits in CD5+ B-1 cell responses following influenza infection." (PMID 31433296, 2019). "Thus, CD5- B-1 cells increase in the MedLN and are a major source of local IgM production after influenza infection." (PMID 31433296, 2019). "CD5+ B-1 cells differentiate to CD5- IgM ASC in the MedLN after Influenza infection." (PMID 31433296, 2019). "The data were unexpected, as we had shown previously that only the CD19+CD43+CD5+but not the CD5- B-1 cells were able to migrate from the pleural cavity to the MedLN after influenza infection, where they differentiated into IgM-secreting cells." (PMID 31433296, 2019). "The percentages of CMV, EBV, flu and IP-30 peptide-specific CD8+ T cells expressing CD5 were not significantly different between the HIV-infected and healthy control groups, either when compared individually or grouped together as non-HIV viral peptide-specific CD8+ T cells." (PMID 25237383, 2014).
peripheral T-cell lymphoma (8 papers, 2006 to 2025). "The patient was diagnosed at an outside laboratory as having a peripheral T-cell lymphoma, supported by the downregulation of CD5 and CD7 in T-cells." (PMID 30687741, 2018). "The tumour cells were CD4+, CD5+ but lacked EMA, TIA-1, CD56 and EBV expression and the diagnosis was a CD30+ peripheral T-cell lymphoma unspecified." (PMID 16623775, 2006). "An ultrasound-guided biopsy of an omental implant was performed, revealing large atypical lymphoid cells positive for CD3, CD2, and CD4, and negative for CD5, CD7, and CD8, with a Ki-67 proliferation index of 90%, consistent with an aggressive peripheral T-cell lymphoma." (PMID 40761963, 2025).
Splenomegaly (8 papers, 2013 to 2024). Abnormal increased size of the spleen. "An older article reported a 38% CD5 positivity, which was associated with bone marrow, splenomegaly, and peripheral blood involvement; 93% had hemophagocytosis, which suggests the possibility of a connection between CD5 positivity and the HPS variant." (PMID 38611591, 2024). "In the CD5-negative group, splenomegaly, lymph node involvement, and hemolytic anemia were significantly less common than in the CD5-positive group." (PMID 37760396, 2023). "HIV Tg26 mice during the last stages of splenomegaly had an expanded immature B cell population consisting of CD19+B220+IgMlowIgD-CD21lowCD23-CD138+CD5+ cell." (PMID 23985023, 2013). "Other entities presenting with lymphocytosis and splenomegaly that may occasionally express CD5 are discussed in the following sections and covered in more detail in the companion articles in this issue." (PMID 34898558, 2021). "Lymphadenopathy was less common (31.5%) in the CD5-negative group than the CD5-positive group (51.4%; p = 0.029), but splenomegaly was more common in the CD5-negative group (42.1%) than the CD5-positive group (16.1%, p = 0.029)." (PMID 37760396, 2023). "The CD5-negative patients frequently expressed a higher level of surface immunoglobulin and were more likely to present with splenomegaly." (PMID 37760396, 2023). "Furthermore, IVLBCL, splenic DLBCL, and primary bone marrow DLBCL often share common clinical, laboratory and immunophenotypic features, including unexplained fever, absence of prominent lymphadenopathy, splenomegaly, high levels of serum LDH and sIL2R, and CD5 positivity." (PMID 31267524, 2019).
squamous cell carcinoma (8 papers, 2014 to 2025). A carcinoma arising from squamous epithelial cells. "When analyzing only thymic squamous cell carcinomas (n = 23), positive CD5 staining remained significantly associated with OS (HR = 0.17, 95% CI: 0.03–0.65, p = 0.009)." (PMID 40242668, 2025). "Strong CK5/6 and P40 expression, commonly seen in squamous cell carcinoma, must be interpreted in conjunction with CD5 positivity to differentiate ITTC from primary squamous cell carcinoma of the thyroid (PSCCT)." (PMID 41476594, 2025). "In the current case, we comprehensively present a clinical, microscopic, molecular, and radiological picture of CD5-positive squamous cell carcinoma of the parotid." (PMID 34807356, 2022). "CD5 was only useful in squamous cell carcinomas in which it was expressed in at least 50% of tumor cells in 10 of 22 (45.5%) tumors." (PMID 35565429, 2022). "More importantly, thymic squamous cell carcinomas are immunoreactive to CD5, which are quite useful to distinguish it from thymic MEC and other non-thymic origin squamous cell carcinoma." (PMID 24444077, 2014). "Notably, monoclonal PAX8 and CD5 antibodies are useful in differentiating ITTC from poorly differentiated thyroid carcinoma (PDTC) and squamous cell carcinoma (SCC)." (PMID 41476594, 2025). "Thus, a marker panel including CD5 and CD117 is helpful in the differential diagnosis of primary lung and primary thymic squamous cell carcinomas with coexpression as a strong argument for a thymic primary." (PMID 26643918, 2015). "Like most of reported cases, the MEC component of our case also presented the immunohistochemical negativity to CD5, supporting the diagnosis of MEC rather than squamous cell carcinoma." (PMID 24444077, 2014). "Interestingly, CD5 and CD117 were both negative in the squamous cell carcinoma, which is often positive for these two markers." (PMID 28095872, 2017).
acute myeloid leukemia (7 papers, 2006 to 2025). Acute myeloid leukemia (AML) is a group of neoplasms arising from precursor cells committed to the myeloid cell-line differentiation. "Aberrant CD7, CD5, cCD79a, and cCD3 were found in 45.8%, 33.3%, 8.3%, and 8.3% of patients with acute myeloid leukemia, respectively." (PMID 36648883, 2023). "For instance, acute lymphoblastic leukaemia (ALL) expresses CD5, CD22 and CD45, while acute myeloid leukaemia (AML) expresses CD15, CD33." (PMID 21614238, 2006). "In Acute Myeloid Leukemia without Maturation CD5, CD7, TdT were aberrantly expressed." (PMID 29805426, 2018).